BATF3 (basic leucine zipper ATF-like transcription factor 3)
Diseases named in the same sentence as BATF3 in open-access papers (continued):
Sharing a sentence is not in itself a finding about the gene and the disease.
tumor (continued). "The capacity of IL-32 to control tumor growth was abrogated in Batf3–/– mice, both in the primary and untreated contralateral tumors." (PMID 32841222, 2020). "Consistent with this notion, the tumor growth delay mediated by intratumoral 17D injection was lost in BATF3−/− mice, especially in non‐injected contralateral tumors." (PMID 31746149, 2020). "Th1 cells, identified by their expression of IFN-γ and TNF-α, were reduced both in frequencies and numbers in the tumor mass of BATF3-/- mice." (PMID 31188899, 2019). "β-Lapachone-induced high mobility group box 1 (HMGB1) release activates the host TLR4/MyD88/type I interferon pathway and Batf3 dendritic cell-dependent cross-priming to bridge innate and adaptive immune responses against the tumor." (PMID 31324798, 2019). "In the case of resistance attributable to a T cell priming defect, restitution of BATF3 DC function can promote T cell‐mediated anti‐tumor immunity." (PMID 31355495, 2019). "Batf3-dependent DCs (CD8α+ or CD103+ DCs) specialize in cross-presentation of necrotic tumor cell-derived epitopes to directly activate CD8+ T cells." (PMID 31324798, 2019). "In the future, it would be interesting to evaluate PU.1, IRF8, and BATF3 efficacy in inducing antigen presentation directly in tumor cells." (PMID 31921109, 2019). "The demonstration of a cell-intrinsic requirement of WDFY4 in cDC1 for immunity against cancer was achieved by comparing tumor growth between Wdfy4−/−:WT vs. Wdfy4−/−:Batf3−/− mixed bone marrow chimera mice." (PMID 30809220, 2019). "Together, these results suggest that FGL2KO tumor cells are more potent than the parental tumor cells at inducing development of Batf3-lineage DCs, which are necessary for initiating an antitumor immune response." (PMID 30683885, 2019). "Batf3−/− mice, a model of cDC1 deficiency, allows to demonstrate their crucial involvement in the initiation of CTL responses leading to tumor rejection." (PMID 31366174, 2019). "Another novel cancer vaccine approach is to stimulate anti-tumor immunity via STING activation in Batf3-dependent dendritic cells (DC) through the use of replication-attenuated VV vectors." (PMID 30626434, 2019). "Their specific loss leads to larger tumors that exhibit reduced infiltration of both CD4+ and CD8+ T-cells, despite the fact that T-cell priming appears to be normal in tumor-bearing BATF3-/- mice." (PMID 31188899, 2019). "Specifically, murine CD8a+CD103+BATF3+CLEC9A+XCR1+ cDC1s have been demonstrated to have a critical role in the cross-presentation of tumor antigens and are generally thought to be indispensable in the development of host anti-tumor immune responses." (PMID 31921140, 2019). "We examine the role of BATF3-dependent CD103+ DCs in models of mucosal and systemic bacterial infection and investigate how BATF3-dependent DCs contribute to T-cell-driven immunity to bacteria and to anti-tumor immunity." (PMID 31188899, 2019). "TGF-β is known to contribute to an overall immunosuppressive microenvironment, promoting cross-talk in the tumor with pathways of stemness such as Wnt/β-catenin, which is correlated with impaired recruitment of BATF3+ DCs." (PMID 31921140, 2019). "In our patient, the tumor thrombus remnant in the segmental vein showed a higher expression of PD-L1 in association with other immune cells including CD8+ T cells and Batf3+ dendritic cells." (PMID 30857555, 2019). "When compared to their normal cellular counterparts, we identified BATF3 as highly and consistently upregulated in the tumor cells of HL and ALCL, and also upregulated in some DLBCL." (PMID 29662618, 2018). "Abscopal effects were abolished in the Batf3−/− mice consistent with other observations demonstrating the critical role of Batf3 DC in regulating RT-induced anti-tumor immune responses." (PMID 30692991, 2018).
tumor (continued). "Tumor-infiltrating BATF3+ dendritic cells have been shown in murine models to be critical for both priming an immune response and for recruitment of effector CD8+ T cells to the tumor microenvironment." (PMID 30400835, 2018). "The presence of tumor-infiltrating BATF3+ dendritic cells correlates strongly with the presence of a T cell-inflamed tumor microenvironment by gene expression profiling." (PMID 30400835, 2018). "These Batf3-dependent DCs are not only required for the initial priming of antitumor T cell responses in the tumor draining lymph nodes but also secrete the appropriate chemokines to attract effector T cells." (PMID 30143632, 2018). "To investigate the potential tumor-initiating capacity of BATF3 in lymphomagenesis of B and T cells, we retrovirally transduced murine mature T and B cells with human BATF3 and transplanted the cells into immunocompromised recipients." (PMID 29662618, 2018). "MDPs and CDPs were sorted from PyMT-B6 tumor-bearing or tumor-free controls and transferred into BATF3−/− mice." (PMID 29593283, 2018). "Batf3-dependent CD103+/CD8α+ dendritic cells (DCs) are critical for cross-presenting tumor antigens in tumor draining lymph nodes (TDLNs)." (PMID 30081947, 2018). "Identifying the cell type(s) involved and the mechanism of non-canonical cross-presentation in regressor tumors can open new therapeutic avenues to stimulate the anti-tumor immune response when Batf3-driven DC1 are excluded from the tumor." (PMID 30400822, 2018). "Tumor-residing Batf3 dendritic cells are required for effector T cell trafficking and adoptive T cell therapy." (PMID 30400822, 2018). "Batf3 dependent DC cells are an important subset of dendritic cells with their ability to efficiently cross-present antigens and regulate tumor growth by enhancing CD8+ T cell migration to the tumor microenvironment and fostering effective T cell response." (PMID 30692991, 2018). "A strong nuclear expression of BATF3 in the tumor cells was confirmed in all cases of HL, in 11 of 21 DLBCL and 14 of 18 ALCL." (PMID 29662618, 2018). "Type I interferon signaling and Batf3-dependent dendritic cells are essential for this mRNA treatment to elicit tumor antigen-specific T cell responses." (PMID 30143632, 2018). "In a similar GEP study of isolated tumor cells of ALCL in comparison to eight subsets of normal mature T and natural killer cells, high BATF3 expression was specifically seen in ALCL tumor cells." (PMID 29662618, 2018). "These T-cells are then able to traffic into tumour sites along chemokine gradients initiated by Batf3+ DCs in the TME." (PMID 29157300, 2017). "Collectively these results demonstrate that Batf3-dependent DCs contribute to the anti-tumour CD8+ T-cell memory response independently of their role in the generation of Trm cells." (PMID 28714465, 2017). "In contrast, radiation given in repeated doses below the dose threshold for Trex1 induction optimally stimulates the cancer cells to produce IFNβ, required to recruit to the tumour and activate Batf3-dependent dendritic cells (DCs)." (PMID 28598415, 2017). "We found that Batf3 significantly contributed to anti-tumour immunity following s.s. of mice with rVACV-OVA." (PMID 28714465, 2017). "Rejection of the irradiated and abscopal TSA tumours in mice treated with 8GyX3+anti-CTLA4 was abrogated in Batf3−/− and interferon-α/β-receptor-1 (IFNAR1)−/− mice, demonstrating the requirement for CD8α+ TIDCs responsive to IFNβ." (PMID 28598415, 2017). "Batf3-dependent DCs cross-present tumour antigens and generate a baseline anti-tumour response that can be potentiated by immunostimulating antibodies in synergy with expansion and activation of this DC subset using Flt3L and poly I:C (refs 17, 18)." (PMID 28714465, 2017). "In recent years, studies in mice have shed light on the vital dual role played by Batf3+ dependent CD8α+ DCs in mediating anti-tumour adaptive immunity." (PMID 29157300, 2017).
tumor (continued). "Batf3 was also required for effective anti-tumour response after i.n. infection with rVACV-OVA and subsequent intravenous (i.v.)challenge with B16-OVA cells." (PMID 28714465, 2017). "Independently of the origin of Tcm cells, transfer to Batf3−/− recipients resulted in impaired anti-tumour immunity with respect to transfer to WT recipients." (PMID 28714465, 2017). "Using Batf3+ knock-out mice, Gajewski and colleagues showed that type I IFN-mediated signalling in Batf3+ dependent CD8α+ DCs was critical for the rejection of immunogenic tumours." (PMID 29157300, 2017). "Batf3-dependent DCs appear to act by restimulating cytotoxic T lymphocyte (CTL) at the tumor site, in part by locally providing IL-12." (PMID 26343581, 2015). "Batf3−/− mice are selectively deficient of the antigen cross-presenting CD8α+ and CD103+DC subsets, which are required for in vivo priming of tumor-specific CD8+ T cells." (PMID 25941586, 2014). "Additionally, the recent finding of BATF3-dependent tumor cell-derived antigen cross-presentation by marginal metallophilic macrophages raises the possibility of an additional cell type contributing to AC cross-presentation in the spleen." (PMID 41212150, 2026). "This is supported by work in mice with Batf3 knockout DCs, which showed that the anti-tumor effects of PD-1 inhibition required both Batf3-dependent DCs cross-presenting antigens to T cells to elicit antigen-specific immunogenic responses and effector T cell attraction to the TME." (PMID 41086813, 2025). "Moreover, similar to NTT tumours, YUMM1.7OVA RTT tumours with Ptgs2 KO or IRF3/7 overexpression were controlled in Rag2–/–Batf3–/– mice, which lack cDC1s." (PMID 39604727, 2025). "Interestingly, in Batf3−/− mice tumor-targeted therapy with BRAFi still worked by controlling tumor growth comparable to C57BL/6 mice, however, resistance developed earlier." (PMID 38631706, 2024). "To investigate this hypothesis, we used Batf3−/− mice and found that increased anti-tumor immunity upon Bcl9/Bcl9l blockade was lost in cDC1-deficiency mice." (PMID 38811552, 2024). "Consistent with the dispensable role of CD8+ T cells in this process, disrupting cDC1-dependent cross-priming of CD8+ T cells using Batf3-deficient hosts did not impair the tumor suppressive effects of NEC immunization." (PMID 38858387, 2024). "Taken together, these findings highlight that in vivo cDC1 reprogramming mediated by PU.1, IRF8 and BATF3 is (i) sufficient to elicit antitumor immunity, (ii) protects from distal tumor growth and (iii) tumor growth after re-challenge, and (iv) the effects are independent of endogenous cDC1s." (PMID 39236156, 2024). "Anti-tumor immunity may depend on the intratumoral presence of both Batf3+ DCs and tumor-specific CD8+ T cells recruited by these chemokines." (PMID 38928238, 2024). "While CD40 agonism broadly activates a variety of hematopoietic cell types that include B cells and macrophages, its activation of DCs, in particular cDC1s, plays an essential role in tumor immunity as illustrated by abrogation of tumor control in murine Batf3-/- models." (PMID 38903502, 2024). "In contrast, the constitutive absence of cDC1 in Batf3-deficient mice not only enhanced the progression of tumors but also abrogated the effect of tumor vaccination to inhibit the growth of tumors." (PMID 39206204, 2024). "Furthermore, it has been observed in several Batf3-/- mouse models that activated DCs are required to promote the anti-tumor efficacy of immunostimulatory antibodies, such as anti-PD-1, anti-PD-L1, and anti-CD137, and deficiencies in DCs limit the efficacy." (PMID 37441069, 2023). "As reflected in the tumor growth curves, we detected a higher proportion of tumor-infiltrating CAR T cells in the BATF3 OE group at the final day 19 time point, probably due to smaller tumor sizes, as the absolute number of T cells were similar between the two groups." (PMID 37945901, 2023).
tumor (continued). "In fact, one candidate identified in this analysis as a potential RIDD substrate is the ER-resident FC receptor Like A (Fcrla), which has been previously identified as part of a BATF3/IRF8 transcriptional program that confers tumor immunogenicity in cDC1s independently of cross-presentation." (PMID 37346037, 2023). "Notably, MC38 and B16-OVA tumour growth was undisturbed by glutamine supplementation in Batf3–/– mice that lack cDC1s29, indicating that the beneficial effect of glutamine treatment requires cDC1s." (PMID 37407815, 2023). "Such an effect required BATF3‐dependent cDC1 dendritic cells that cross‐present tumor antigens." (PMID 37782273, 2023). "Given the enhanced tumor control conferred by BATF3 OE in CD8+ T cells, we investigated whether BATF3 OE programmed a transcriptional signature associated with clinical response to ACT." (PMID 37945901, 2023). "Consistent with the dispensable role of CD8+ T cell in this process, disrupting cDC1-dependent cross-priming of CD8+ T cells using Batf3-deficient hosts did not affect the tumor suppressive effect of NEC immunization." (PMID 38196632, 2023). "Again, we observed superior tumor control with BATF3 OE CAR T cells across both donors." (PMID 37945901, 2023). "The results again demonstrated that CD39i could effectively inhibit tumor growth and improve the prognosis of tumor-bearing Batf3+/+ mice." (PMID 36347860, 2022). "Tumor-specific T cells were undetectable in Batf3–/– tumor-bearing mice." (PMID 35393950, 2022). "The therapeutic effect of Flt3L+NDV was completely lost in Batf3−/− mice, despite similar increase and activation of total cDCs and pDCs in the tumor and TdLN upon Flt3L+NDV treatment; an increased proportion of cDC2s was observed, possibly to compensate for the lack of cDC1s." (PMID 36418317, 2022). "Additionally, the protein expression of SETDB1, BATF3, and PD-L1 was diminished while FOSB expression was upregulated in the presence of sh-SETDB1+OE-NC while opposite results were detected in the tumor tissues of mice treated with sh-SETDB1+OE-BATF3." (PMID 35497876, 2022). "Our investigation of tumor-specific T cells in Batf3–/– mice unmask unique mechanisms." (PMID 35393950, 2022). "However, immune cell number normalized to tumor gram was dramatically decreased in Batf3–/– mice, which was probably due to increased tumor size." (PMID 35393950, 2022). "Thus, despite some benefit of αCD40 in Batf3–/– mice, mice required euthanasia due to achieving a tumor radiance of >108 by day 14, indicating cDC1s are required for long-term durability of αPD-L1 + αCD40 therapy." (PMID 35393950, 2022). "Notably, the necrotic cells transplanted into the TME stimulate the antitumor immune response mediated by BATF3 + cDC1- and CD8 + leukocytes and are accompanied by tumor-associated antigen-presenting cells, which increase the tumor antigen load." (PMID 36482419, 2022). "In contrast, our studies demonstrated early defects in anti-tumor effects and anti-tumor IFN-γ production in tumor, TdLNs, and blood of CD8+ T cells in Batf3-deficient animals, even when studying anti-GFP (Batf3-wt) transferred T cells." (PMID 36418317, 2022). "However, while virus-reactive T cells were mostly maintained in Batf3−/− mice, treatment completely failed, demonstrating the importance of tumor-specific CD8+ T cells for NDV-induced tumor control." (PMID 36418317, 2022). "More cells acquired EGFP and expressed higher EGFP levels in Batf3–/– than Batf3+/+ hosts, which could be due to greater tumor burden." (PMID 35393950, 2022). "We observed fulminant tumor growth in Batf3–/– mice and decreased survival." (PMID 35393950, 2022). "All 3 intratumoral myeloid subsets acquired tumor antigen in both Batf3+/+ and Batf3–/– hosts." (PMID 35393950, 2022). "CD40 agonist primes tumor-specific CD8+ T cells via monocytes/macrophages in Batf3–/– mice." (PMID 35393950, 2022).
tumor (continued). "Notably, there was a significant decrease in both frequency and number of donor CD8+tetramer+ Teff and memory T cells in both the spleen and tumor of Batf3–/– recipients." (PMID 35393950, 2022). "Unexpectedly, agonistic αCD40 + αCD4 induced tumor-specific CD8+ T cell expansion in Batf3–/– mice." (PMID 35393950, 2022). "The restoration of BATF3 recruitment and activation of tumor microenvironment could contribute to effector T cell accumulation and clinical activity." (PMID 35497876, 2022). "Taken together, our findings indicate that the unique migratory phenotype of tiDC2s from Batf3–/– mice is likely the result of tumor microenvironment changes and is not caused by altered DC development." (PMID 34283809, 2021). "Furthermore, CD40 is moderately correlated with BATF3 (dendritic cells) in normal (r = 0.30) and tumor (r = 0.36) tissues." (PMID 34758832, 2021). "Interestingly, the proportion of deaths due to left tumor outgrowth increased in BATF3-KO mice treated with CART-gp75/Saline, as compared with WT mice treated similarly." (PMID 34810235, 2021). "Since Flt3L-mediated expansion of Batf3-dependent DCs boosts tumor-specific CD8+ T cells, we tested whether Flt3L effect on cDC1s could be affected by DNGR-1 in the context of tumors." (PMID 33980589, 2021). "Having ruled out the cytotoxic effectors, we hypothesized that increased CD4+ T cell tumor infiltration is key to the antitumor response in Batf3–/– mice." (PMID 34283809, 2021). "In addition, activation of intra-tumoral Batf3-DCs was required for optimal trafficking of CD8 T cells into the core of the tumor, a process mediated by CXCL9 secretion." (PMID 34276686, 2021). "Activation of Wnt/β-catenin pathway in cancer cells inhibits secretion of CCL4 that is required for the recruitment of BATF-3 dependent dendritic cells to the tumor micro-environment, resulting in reduced levels of DC-derived CXCL10 and limited CD8+ CTL infiltration and cross-priming." (PMID 34774008, 2021). "The central role of CD4+ T cells for control of PyMT tumors in Batf3–/– mice could be a bystander effect of an overall stimulatory tumor microenvironment or a de novo T cell response generated directly by tiDC2s." (PMID 34283809, 2021). "Similarly, there was little difference in tumor infiltration of immature myeloid cells (CD11b+Ly6c+MHCIIlo) in Batf3–/– mice compared with WT mice." (PMID 34283809, 2021). "Support for this hypothesis has been demonstrated in-vivo, where versikine-overexpressing murine lung, breast and myeloma tumours displayed a significant increase in Batf3-expressing dendritic cells when compared to tumours from empty-vector control cells." (PMID 33187209, 2020). "Deficiency of cross-presenting DC (in Batf3–/– mice) or CD8+ T cells abrogated the therapeutic efficacy of IL-32 in mice, suggesting that the IL-32 effector mechanisms are dependent on cDC1 priming of tumor-specific CD8+ T cells." (PMID 32841222, 2020). "Moreover, BATF3-DCs perceive the IFN secreted from irradiated tumor cells and then recruit on the tumor cells, which is indispensable for the cross-priming of T cells to exert an anti-tumor function." (PMID 32992835, 2020). "Experiments utilizing Batf3−/− mice lacking cross-presenting DCs failed to control syngeneic fibrosarcomas that were rapidly rejected in wildtype mice, with a lack of tumor-specific CTLs implicated." (PMID 32121071, 2020). "Analysis of these tumours in the setting of the ovalbumin-OT-I, a model antigen expression system, confirmed an increase in antigen-specific CD8+ T-cells in versikine-expressing tumours providing confirmation of the capacity of Batf3-expressing dendritic cells to drive anti-tumour immunity." (PMID 33187209, 2020). "Conversely, tumor-bearing Batf3-deficient mice demonstrated non-responsiveness to anti-PD1, anti-PDL1 and anti-CD137 checkpoint blockade." (PMID 32121071, 2020).